EPO (erythropoietin)
Diseases named in the same sentence as EPO in open-access papers (continued):
Sharing a sentence is not in itself a finding about the gene and the disease.
anemia (continued). "HIV infection of marrow stromal cells, decrease in serum erythropoietin levels, auto-antibodies to erythropoietin, or marrow suppression by opportunistic infections, may contribute to the anemia commonly observed in HIV-infected patients." (PMID 29568529, 2018). "Recombinant human erythropoietin and the analogs are widely used to treat anemia." (PMID 30741617, 2018). "We extended our observations to determine if our T-lymphocyte-based method of EPO delivery could effectively reverse anemia of chronic kidney disease in the adenine nephrotoxicity model." (PMID 29636469, 2018). "Given the high prevalence of anaemia, further well-designed trials across multiple surgical specialties, addressing the limitations we have identified, are required to determine the true safety and efficacy of IV iron ± EPO." (PMID 30559962, 2018). "Chronic kidney disease is a relatively frequent comorbidity in cancer patients, which can contribute to anemia not only through a reduction of EPO synthesis, but also through increased hepcidin levels leading to iron trapping within the macrophages, and eventually to FID." (PMID 30274354, 2018). "The pro-erythropoietic factor erythropoietin (EPO) is often employed for anemia therapy." (PMID 30158520, 2018). "Role of EPO during malarial anemia still remains controversial." (PMID 30586912, 2018). "Two of the most advanced drugs developed by screening phage-displayed libraries of random peptides are the EpoR and TpoR peptide agonists that target the erythropoietin and thrombopoietin receptors for the treatment of anemia and idiopathic thrombocytopenic purpura respectively." (PMID 29485998, 2018). "Anaemia remains highly prevalent requiring treatment with erythropoietin and transfusions." (PMID 30290796, 2018). "Erythropoietin synthesis is also decreased, potentially leading to anemia." (PMID 30538746, 2018). "In contrast, 50 mg/kg of adenine daily for 28 days showed severe renal dysfunction (plasma creatinine 1.9 ± 0.10 mg/dL) and anemia (hematocrit 36.5 ± 1.0% and EPO 28 ± 2.4 pg/mL) as compared with vehicle-treated mice (0.4 ± 0.02 mg/dL, 49.6 ± 1.6% and 61 ± 4.0 pg/mL, respectively)." (PMID 29415057, 2018). "This study showed that neonatal kidneys with AOP were not hypoxic regardless of anemia, therefore the lack of hypoxia signaling was considered to be a cause for the EPO deficiency." (PMID 29535446, 2018). "Systemic EPO concentration is dynamically regulated by the presence of hypoxia or anemia." (PMID 30108502, 2018). "Most anaemia resolves by 3–6 months with restoration of erythropoietin levels." (PMID 30290796, 2018). "Notably, pure-red cell aplasia (PRCA), a sudden severe anemia, was developed in patients treated with Eprex® rh erythropoietin." (PMID 29973504, 2018). "The insufficient renal EPO production in anemia at P7 was considered to be the same as AOP." (PMID 29535446, 2018). "In their study, human ECFCs that were genetically engineered to overexpress erythropoietin (EPO) were shown to form vascular networks that increased erythropoiesis and corrected anemia in the recipient mice, revealing the engineered network’s potential to serve as a drug delivery device." (PMID 29766399, 2018). "Also, in COPD patients with anemia, hemoglobin level and erythropoietin level are inversely correlated, which suggests a decrease in hematopoietic response to erythropoietin." (PMID 30355325, 2018). "Anaemia is the consequence of a decrease in erythropoietin production in fibrotic kidneys." (PMID 28857467, 2018). "As a future perspective, the potential benefic effects of tarin administration could be explored as a chemotherapy adjuvant to treat anemia, leukopenia and sensitizing erythroid progenitor cells to erythropoietin." (PMID 30403726, 2018).
anemia (continued). "We evaluated anemia prevalence and treatment (erythropoietin stimulating agents [ESAs], intravenous [IV] iron, red blood cell [RBC] transfusions) following anemia diagnosis during a 1-year baseline period, and healthcare utilization during a 1-year follow-up period." (PMID 29544446, 2018). "In conclusion, although G-CSF combined with EPO has been administered to treat anemia in patients with MDS, aplastic anemia, and HIV for many years, the mechanism through which G-CSF promotes erythropoiesis remains unclear." (PMID 29720275, 2018). "However, the EPO levels in renal anemic patients remain generally normal or slightly increased, considered inappropriately low relative to the degree of anemia." (PMID 30108502, 2018). "In anemia of cancer, erythropoietin levels were reported to be inadequate low." (PMID 30089125, 2018). "We therefore speculated that JPYS might stimulate EPO expression via HIF signaling in achieving for the treatment of CKD anemia." (PMID 29615029, 2018). "We propose that inhibition of P38α, by enhancing erythropoiesis in an EPO-independent fashion, may provide an alternative strategy for the treatment of anemia." (PMID 30158520, 2018). "In addition, EPO expressions were detected in the liver and spleen with the progression of anemia, suggesting a possible compensatory mechanism to accelerate erythropoiesis." (PMID 30586912, 2018). "In patients with anemia who received erythropoietin with dose requirements based on weight and anemia and without any another cause for anemia, evaluate for PRCA and anti-rHu-EPO antibody level were measured by ELISA." (PMID 28042550, 2017). "Thus, it is our objective to determine this effect on hemodialysis patients in whom anemia is very common despite of treatment with erythropoietin." (PMID 28487874, 2017). "Interestingly, when EPO signaling is activated using recombinant EPO, cardiac dysfunction is diminished and anemia is relieved through stimulation of erythropoiesis." (PMID 28850611, 2017). "Recombinant human erythropoietin (EPO) is standard treatment for anemia in cancer patients." (PMID 28415825, 2017). "Prolonged EPO administration, as is often prescribed in clinical conditions such as anemia, may pose a challenge to the liver." (PMID 28871174, 2017). "Inflammatory cytokines such as interferon-γ, tumor necrosis factor-α, interleukin-1, and interleukin-10 might compromise iron metabolism, impair erythroid progenitor cell proliferation, and blunt erythropoietin response to anemia." (PMID 29237417, 2017). "Thus we concluded that, correction of anemia by higher dosage of erythropoietin can decrease or resolve RLS symptoms in dialysis patients." (PMID 28497091, 2017). "Thus, when hypoxia, anemia, or iron-deficient conditions are present, stabilization of HIF-2α induces erythropoietin (EPO) expression and red blood cell (RBC) development, thereby consuming iron via hemoglobin synthesis." (PMID 28375184, 2017). "Inadequate erythropoietin production is the primary feature of anemia in patients with CKD." (PMID 29237417, 2017). "These EPOR2/βcR2-independent pathways seem to be favorable in transplant medicine, since low-dose EPO is used frequently for anemia treatment in clinical medicine and has not been linked to severe adverse events such as thrombosis." (PMID 29127105, 2017). "We focussed upon EPO production as numerous confounding factors may have influenced Hb levels over this time period including hemodilution due to fluid infusion, anemia of inflammation, repeated blood sampling, and other blood losses." (PMID 28335733, 2017). "In general, serum erythropoietin levels were inversely related to the severity of the anemia." (PMID 28135344, 2017). "Treatments include termination of recombinant erythropoietin use, correction of anemia by blood transfusion if necessary, kidney transplantation as the most effective treatment, prescription of cyclosporine A, or cyclophosphamide with corticosteroid to suppress the immune system." (PMID 28042550, 2017).
anemia (continued). "Indeed, these data are consistent with previous literature showing that malaria induces an EPO-independent anaemia." (PMID 28938907, 2017). "Erythropoietin (EPO) is a well-known hormone that is clinically used for the treatment of anemia." (PMID 28383559, 2017). "Erythropoietin (EPO) is critical for erythrocyte production in response to anemia." (PMID 28542307, 2017). "Furthermore, the treatment of preoperative anaemia with RBC transfusions is more costly as compared to correcting anaemia with haematinics like iron, vitamin B12, folate, or erythropoietin substitutes preoperatively." (PMID 29375620, 2017). "Anemia treated with recombinant human erythropoietin (rHu-EPO)." (PMID 28042550, 2017). "Moreover, a negative correlation between Hb levels and inflammatory markers was found in poor EPO responders, indicating that the severity of anemia correlates with the state of inflammation." (PMID 27889956, 2017). "Through recombinant DNA technology, recombinant EPO (rhEPO) is now one of the most widely used drugs to treat anemia in patients with chronic kidney disease (CKD), acquired immune deficiency syndrome, multiple myeloma, myelodysplastic syndromes, and chemotherapy-induced anemia." (PMID 31557985, 2016). "A central concern, however, in the use of EPO to treat anaemia in cancer patients is whether tumour cells express EPOR and therefore could be stimulated to tumour growth." (PMID 27581518, 2016). "Although EPO and G-CSF have been commonly used individually as hematopoietic growth factors in the treatment of anemia and neutropenia, these pharmacological agents have been recently reported to have neuroprotective and regenerative potential as neurotrophic factors in stroke." (PMID 27043535, 2016). "In fact, a similar transient discrepancy between bone marrow iron availability and requirements during increased erythropoietic activity is observed despite the use of oral iron supplements in chronic dialysis patients and healthy individuals who received EPO treatment for anemia." (PMID 27068103, 2016). "While in patients EPO is typically administered for the anemia associated with the disease, in the 5T33MM mouse model we did not account for Hgb levels at the time of EPO administration." (PMID 27481313, 2016). "This study investigates whether erythropoietin levels are inappropriately low in these cases of “anemia of unknown etiology” and whether this trend persists after accounting for confounders." (PMID 27310832, 2016). "This suggests that decreased EPO production or a blunted EPO response to anemia may play a role in the pathogenesis of AUE and that this may indeed constitute a distinct entity." (PMID 27310832, 2016). "Endogenous secretion of erythropoietin (EPO) may be overwhelmed by the high demand for erythropoiesis stimulation that is required to meet the rapid development of anaemia during the patent period." (PMID 27618936, 2016). "EPO elevates red blood cell count, hemoglobin and hematocrit peripheral blood system, which results in the improvement of quality of life in patients with anemia." (PMID 26575329, 2016). "The anemia, accompanying the disease is often treated with recombinant human EPO." (PMID 27481313, 2016). "Of the 1246 patients with anemia, 496 (39.8%) received EPO treatment (493 received EPO-α)." (PMID 27310973, 2016). "According to Tang, any abnormality that reduces renal secretion or bone marrow responses to erythropoietin may result in anemia." (PMID 27974990, 2016). "A better understanding of the osteoimmunological roles of EPO may advocate for the use of rHuEPO along with targeted bone protective treatment in MM patients, to attenuate the anemia and MM progression, while also preventing bone damage." (PMID 27481313, 2016). "In addition, nephrotoxic effects of particular cytotoxic agents, such as platinum salts, can also lead to the persistence of anemia through reduced EPO production by the kidney." (PMID 27142617, 2016).
anemia (continued). "When physicians manage anemia only by controlling the hemoglobin level with erythropoietin-simulating agents, few would notice whether the use of cinacalcet improved the anemia." (PMID 27764168, 2016). "Thus, therapeutic manipulation of the HIF system has substantial medicinal potential, e.g. by promoting EPO production for the treatment of anemia or by down-regulating VEGF production in tumors." (PMID 27502280, 2016). "In patients with diabetes, anemia may be the result of diminished EPO production by the failing kidney." (PMID 27142617, 2016). "In addition, VH298 is also able to stimulate the production of endogenous EPO, indicating its potential to benefit patients with anemia resulting from insufficient EPO synthesis." (PMID 27811928, 2016). "This suggests that decreased erythropoietin production may play a key role in the pathogenesis of anemia of unknown etiology." (PMID 27310832, 2016). "Given that erythropoietin deficiency plays a major role in the anemia of CKD, this pathway seems unlikely to be involved based on the results of the current study." (PMID 26823182, 2016). "We have shown that erythropoietin levels are inappropriately low in anemia of unknown etiology, even after adjusting for confounders." (PMID 27310832, 2016). "Given that GDF11 has been shown to inhibit erythroid maturation in mice, elevation of GDF11 levels may be involved in erythropoietin-resistant anemia in HD patients." (PMID 27298756, 2016). "Therefore we decided to use the group of patients with IDA for an approximation of the normal EPO response since patients are expected to demonstrate a more or less physiologic EPO response to anemia." (PMID 27310832, 2016). "Indeed, as many as 70% of the present study subjects had anemia and were receiving an erythropoietin-simulating agent." (PMID 27764168, 2016). "Accordingly, we found that AKI mice showed a transient reduction of EPO levels and a light anaemia." (PMID 27853265, 2016). "Among the tested traits, tubulointerstitial injury (tubular index) and anemia (Hb and Ht) were strongly associated with the same locus on Chr 2, possibly because, in patients with CKD, anemia develops due to decreased renal erythropoietin synthesis resulting from tubulointerstitial damage." (PMID 27230548, 2016). "Preoperative administration of recombinant human erythropoietin may correct preoperative anemia and, thus, the need for transfusion, although this practice has not yet been widely adopted." (PMID 27832187, 2016). "Anemia treatment with erythropoietin (EPO) in CKD patients seems to have a pleiotropic effect and may reduce chronic inflammation, oxidative stress, and immune cell apoptosis." (PMID 27034745, 2016). "Early studies posited that treatment of anemia with erythropoietin might have salutary effects on brain function among patients with ESRD receiving dialysis." (PMID 26823182, 2016). "The mainstay of treatment for anemia in patients with CKD is use of either EPO or iron products." (PMID 27310973, 2016). "The physiopathology of anaemia associated with CKD can be explained by two mechanisms: firstly, a decrease in erythropoiesis owing to a decrease in the production and secretion of erythropoietin (EPO) and secondly the occurrence of a disorder of iron metabolism." (PMID 27313944, 2016). "Another hypothesis for the persistence of the anemia in CRF rats is that an altered activity/function of EPO has occurred, resulting from kidney cell damage, supported by previous reports." (PMID 26712750, 2015). "Our data also suggest that the anemia of CKD and the associated kidney hypoxia favour the development of fibrosis, angiogenesis and a local inflammatory milieu in the kidney that seem to underlie a “resistance” to EPO stimuli and reduced iron availability." (PMID 25867633, 2015).
anemia (continued). "The depletion in L-carnitine is associated with important clinical problems and symptoms, most notable of which are anemia hyporesponsive to erythropoietin therapy, intradialytic hypotension, cardiomyopathy and skeletal muscle dysfunction manifested as generalized fatigability." (PMID 26612997, 2015). "In hypothyroid conditions, reduced EPO levels are the most important determinant of anemia." (PMID 26779261, 2015). "However, several studies failed to prove the effectiveness of transdermal androgen therapy in increasing EPO levels in anemia of chronic kidney disease or in healthy older men with serum T concentration <475 ng/dL." (PMID 26779261, 2015). "One compound, FG-2216, has been shown to increase EPO levels in patients with end-stage renal disease, while another compound from the company, FG-4592, has been shown to correct anemia in patients with peritoneal dialysis and patients undergoing dialysis without iron supplementation." (PMID 26491535, 2015). "Also longitudinal studies on iron, folate, cobalamin levels and bone marrow examination, erythropoietin and viral load determination, are needed to determine the actual etiology of anemia in HIV infected children." (PMID 26413303, 2015). "Finally, several trials were designed in order to address the effect of EPO replacement therapy on anemia and IGF-1." (PMID 26779261, 2015). "Surge of reticulocytes is a common feature of different types of anemia and may be a consequence of higher plasma levels of erythropoietin that we have shown." (PMID 26161863, 2015). "Many domestic cats suffer from CKD, and EPO can improve CKD-induced anemia." (PMID 25671605, 2015). "In other words, the pathogenesis of anemia in the early stages of CKD might be heterogeneous in terms of the severity of impairment of EPO productivity and responsiveness." (PMID 25884723, 2015). "Exercise has been associated with EPO administration in order to test if, beyond affecting anemia, EPO could further improve exercise effects on muscle wasting." (PMID 26636649, 2015). "In addition, IBD individuals can have difficulty in utilizing iron appropriately because it has low levels of erythropoietin for their severity of anemia." (PMID 25705682, 2015). "On the other hand, the 3rd article (PMC3790708) does not focus on the association between erythropoietin and anemia, and hence it was not selected by the biomedical experts for the association." (PMID 26440794, 2015). "We did not measure more accurate markers of inflammation, but several studies have clearly demonstrated that CRP levels positively correlate with the severity of anemia and EPO resistance in CKD patients, and that CRP concentrations closely reflect Interleukin-6 levels." (PMID 25781618, 2015). "It has also been reported that effective erythropoietin synthesis may be impaired following pathologic conditions of the kidneys, contributing to the anaemia observed in diabetes mellitus." (PMID 26697217, 2015). "We must also consider the hypothesis that the endogenous EPO concentration is inadequate to overcome anemia." (PMID 26712750, 2015). "However, treatment is not based solely on EPO administration; antiproliferative cytokines and stimulation of iron uptake are used in combination with EPO in attempts to reverse the anemia." (PMID 26538835, 2015). "During the follow-up period (median 959 days, range: 7-3595 days), 84 (48%) patients developed anemia (new anemia in 48 patients, further development of anemia in 32 patients, initiation of iron supplementation in 2 patients and initiation of EPO in 2 patients)." (PMID 25884723, 2015). "However, in spite of increased EPO production during Salmonella infection, the proportions of RBCs in systemic circulation decline leading to anemia." (PMID 26068006, 2015). "The persistence of anemia may result from a dysfunctional EPO or from reduced iron availability, as suggested by the low serum iron and transferrin levels." (PMID 25867633, 2015).